C3 (complement C3)
Diseases named in the same sentence as C3 in open-access papers (continued):
Sharing a sentence is not in itself a finding about the gene and the disease.
infection (continued). "It is noteworthy that additional factors, such as e.g. infection or subsequent more subtle thromboembolic events that can contribute to high systemic C3 levels and negative outcome in the CE patients, could have also affected the results." (PMID 23977229, 2013). "Moreover, only mice lacking C3 were partially protected early in infection and this early phenotype was also absent in C5def or C5aR−/− mice." (PMID 23189195, 2012). "Therefore, reduced cytokine secretion in A549 cells lacking C3 indicates impaired protective inflammatory function, which may translate to a compromised immune response to infections." (PMID 41441980, 2025). "ANCA-negative PICG may be triggered by bacterial infections, including Klebsiella pneumoniae, Streptococcus parasanguinis, and Staphylococcus epidermidis, with renal involvement typically occurring within zero to three days of infection and presenting with or without low serum C3 levels." (PMID 40755685, 2025). "Elevated numbers of CD11c+MHCIIhighCD11b+ DCs in absence of C3, C3aR, and/or C5aR1 in the lung on day 6 p.i might additionally indicate decreased complement-dependent recruitment of this cell type to the infected lung at later stages of infection." (PMID 33767691, 2021). "Deletion of Bmal1 in primary Bmal1fl/fl neuron cultures via infection with an AAV8-Cre viral vector (versus AAV8-eGFP control) suppressed the BMAL1 transcriptional target Nr1d1 (which encodes REV-ERBα) by 85% and induced C4b expression but caused no increase in C3." (PMID 33258449, 2020). "Furthermore, C3 may be cleaved into C3b by certain non-specific proteases, especially at sites of inflammation, coagulation, and infection." (PMID 29670616, 2018). "Overall, these data demonstrate the efficacy of BLI in examining host determinants of pathogenesis and indicate that C3 contributes to, but is not essential for, the clearance of an NMII infection in vivo." (PMID 40586810, 2025). "Next, co‐infection assays with TbCSVdC3 and PVX vector expressing each of the C3 truncated mutants were performed, and the combinations TbCSVdC3/C3 and TbCSVdC3/PVX served as positive and negative controls, respectively." (PMID 40025647, 2025). "In response to infection, an increase in the expression of MIP1a, MIP1b, and MCP-1 proteins is observed in the lung regardless of the presence or absence of C3, indicating that some inflammatory signals remain intact in the absence of the complement component." (PMID 35204727, 2022). "There were no statistical significance of the plasma concentrations of C1q, FB, MBL, C3, C3a, C4, C4a and sC5b-9 between the HBV-ACLF patients with infection and the HBV-ACLF patients without infection." (PMID 32293297, 2020). "When complement factor B was considered, Control AMs did not produce detectable amounts of the molecule, but as for C3, ΔLasB-PAO1 infection upregulated that factor, albeit to lesser levels (from 0 to 3 ng/mL)." (PMID 30083156, 2018). "According to our data, there was little variation in the complement C3 levels between SLE patients with and without infection." (PMID 29267496, 2017). "However, there is no indication in the literature of the use of apolipoprotein A-I, complement C3 and protein C-reactive for differentiation between patients with acute bacterial meningitis, patients with enteroviral meningitis, and individuals without infection in the CNS." (PMID 26040285, 2015). "We previously reported that the absence of C3 accelerated cornea pathology following HSV-1 infection, but this increase in corneal opacity and neovascularization was not due to changes in infectious virus recovered in the cornea 3–7 days post infection (PI)." (PMID 38251381, 2024). "The similar complement C3 response in ABU and UTI patients may indicate that ABU should be reconsidered as an infection albeit without symptoms." (PMID 33672892, 2021).
infection (continued). "However, the concentrations of anti-ds-DNA, complement C3, complement C4, and globulin did not significantly differ between SLE patients with and without infection." (PMID 29267496, 2017). "Therefore, we analyzed globulin, complement C3 and complement C4 levels in SLE patients with and without infection." (PMID 29267496, 2017). "However, complement C3, complement C4, globulin, and anti-ds-DNA levels were not significantly different in SLE patients with and without infection." (PMID 29267496, 2017). "Furthermore, a broad activation pattern of the complement system—encompassing both effector components (e.g., C2, C3, C8A, C9) and regulatory proteins (e.g., CFH, CFI, C1QB)—is consistent with prolonged innate immune stimulation in the absence of active infection." (PMID 40869330, 2025). "We and others have demonstrated, after infection of highly differentiated, pseudostratified human airway epithelial (HAE) tissue cultures and lung organoids with SARS-CoV-2 VoCs, that substantial mobilization of intracellular complement-C3 occurs within the nonimmune epithelial barrier." (PMID 38419061, 2024).
tumor (398 papers, 1976 to 2026). "In previous reports, which indicated that tumor cell-derived C3 contributes to an immunosuppressive tumor microenvironment (TME) by activating the C3a-C3aR-PI3Kγ signaling pathway in tumor-associated macrophages (TAMs), thereby repressing antitumor immunity." (PMID 40396123, 2025). "Clinically, C3 and C5 inhibitors have been explored for their potential to improve immune checkpoint blockade efficacy and limit tumor-associated inflammation." (PMID 40283026, 2025). "Hypoxia (low oxygen conditions) is well known to contribute to radioresistance in tumours, and a hypoxic tumour microenvironment is associated with upregulated local C3 and C3aR expression in astrocytes and glioblastoma cells." (PMID 39765018, 2025). "Ligation of MBL was shown to be essential for PDA progression: deletion of Mbl (encoding MBL) or C3 in the extratumoral compartment, as well as knockdown of the C3a receptor (C3aR) in tumor cells, significantly suppressed tumor growth." (PMID 41163402, 2025). "These particular cancer cells also activated complement pathways and secreted complements such as C1S, C1R, and C3, which facilitated the recruitment of tumor-associated macrophages (TAMs) and T cells." (PMID 38951896, 2024). "In vitro cancer cell lines and mice models showed that the C3 protein suppresses antitumor immunity by modulating tumor-associated macrophages." (PMID 38383923, 2024). "A third protein-protein interaction network in the blood cancer patient group includes genes associated with the complement system such as C1S, C3 and C8A, activation of which is mainly associated with pro-tumour effects." (PMID 36649303, 2023). "C3-liposomes bind complement C3, which interacts with C3-receptors on APCs, resulting in liposomal uptake and the delivery of tumor antigens to APCs in a manner that mimics pathogenic uptake." (PMID 38140114, 2023). "For instance, mice deficient of the C3, C4, or C5aR components showed inhibition in their tumor growth in mice." (PMID 35173724, 2022). "In tumor cells, loss of MBL or complement C3 in the equatorial region and deletion of the complement C3a receptor (C3aR) can prevent tumor progression." (PMID 36510609, 2022). "These neutrophils were found to promote tumor growth, as their depletion resulted in reduced tumor growth similar to that observed in C3 deficient mice." (PMID 35860237, 2022). "The improved efficacy of the anti-CD20, largely dependent on CDC, was associated with increased deposition of C3 and C9 in the tumor." (PMID 35860237, 2022). "Our data showing a strong protective effect of C3 deficiency in cSCC would be consistent with the idea that C3 activation fragments can act as tumor-promoting GFs by orchestrating the immune microenvironment and modulating the adaptive immune response." (PMID 32682912, 2021). "C3 overexpression was significantly associated with advanced clinical stages; later stages of tumor, nodes, and metastases (TNM) classification; and high death rate (all P < 0.05)." (PMID 34688260, 2021). "Intriguingly, loss of C3 expression in LNM tumour cells was associated with shorter 3-year overall survival." (PMID 33658651, 2021). "We used multi-omics approaches to evaluate the association of complement signature C3/C5/C3AR1/C5AR1 with tumor immune phenotypes and prognosis across various cancer types." (PMID 34439277, 2021). "In this study, we combined transcriptomic data from public databases with our own work and found that complement component 3 (C3) gene was associated with oxaliplatin resistance via reprogramming the tumor immune microenvironment in CRC." (PMID 34722636, 2021). "Analysis of differential gene expression at different tumor stages revealed an association between tumor stages and high gene expression of C3 in THCA and KIRC; C3AR1 in SKCM; and C5AR1 in BLCA, THCA, and SKCM." (PMID 34439277, 2021).
tumor (continued). "Guided by these observations, we investigated the tumor susceptibility of C3-deficient (C3−/−) mice and found that these mice were markedly protected from tumor development." (PMID 32682912, 2021). "The oncogenic activity of C3a has been demonstrated in mice with tumor growth mitigation due to deficiency of C3 or its receptor, suggesting a crucial role of this pathway in tumor development." (PMID 34298645, 2021). "In consistent, the counterpart tissues of C5- and C5ar1-deficient mice were infiltrated with significantly greater numbers of CD8+ T cells compared with the tumor tissues of WT and C3-deficient mice." (PMID 32754267, 2020). "The treatment with a copper compound with cytotoxic properties induced the decrease in the HSP60 levels, the separation of the complex HSP60/pC3, and consequently, the C3 activation of the caspase pathway associated with a tumor-cell growth arrest." (PMID 31963896, 2020). "Kwak and colleagues also observed enhanced IL-10 expression in CD4+ and CD8+ T lymphocytes in lungs of tumor-bearing C3-deficient mice." (PMID 31379815, 2019). "Complement molecules, such as C3, have also been associated with the initiation of metastasis by contributing to epithelial-to-mesenchymal transition of tumor cells in primary tumors." (PMID 31331124, 2019). "NFAT family includes four classic members: c1, c2, c3 and c4 which were first described in immune cells and have been associated with malignancies and tumour progression (reviewed in6,7)." (PMID 31249342, 2019). "The abundance of complement C3 with mannose‐5 or mannose‐6 glycoform at Asn85 was associated with HCC tumor grade." (PMID 31136099, 2019). "Genetic ablation of PTX3 results in a factor H-mediated increase of C3 complement component deposition, thus leading to a pro-tumor inflammatory context that confers increased susceptibility to mesenchymal and epithelial carcinogenesis." (PMID 31533326, 2019). "The concentration of complement C3 with Man5, Man6, or Man7 glycoform at Asn85 closely linked to the tumor grade and the association was stronger than did α‐fetoprotein, a renowned HCC biomarker." (PMID 31136099, 2019). "In 2008, complement C3, C4, and C5a receptor 1-deficient mice were shown to have slower tumor growth in a model of human papilloma virus-induced cancer." (PMID 30061895, 2018). "A Cox regression using univariate analysis indicated that postoperative C3 levels, pathological T stage, N stage, and total tumor stage (pTNM), and tumor marker were associated with long-term survival." (PMID 29062836, 2017). "In clinical non-tumor liver tissues, hepsin levels were positively associated with C3 expression, which strongly suggests that hepsin is required for C3 production in normal liver." (PMID 26760961, 2016). "C3 deficiency leads to altered immune response in experimental ovarian cancer causing a decrease in tumor development and progression." (PMID 25657649, 2015). "C3, C4, or C5aR deficiencies prevent tumor growth in mice, potentially via inhibition of the CP and the generation of C5a, which has a potent inflammatory potential." (PMID 26074922, 2015). "It has been shown that C3 or C4 deficiency and complement-activation products inhibition result in greatly reduced tumor growth." (PMID 25789864, 2015). "This provides a mechanism by which C3 activation from the superficial peritoneal endometriotic lesion epithelium promotes the pro-lesion macrophage phenotype described as pro-repair, tumor-associated, or M2 which contributes to tissue remodeling including neovascularization and fibrosis." (PMID 39935459, 2025). "Both C3 and C4 have emerged as constituents of tumor-promoting inflammation, implicated in immune modulation by activating protumorigenic neutrophils and tumor-associated macrophages as well as inducing PI3K/AKT-dependent tumor cell proliferation and epithelial-mesenchymal transition." (PMID 38285640, 2024). "CFB, C3, and C5 are commonly associated with changes in the tumor microenvironment." (PMID 37628784, 2023).
tumor (continued). "Furthermore, the components C3 and C3a were reported to play crucial roles in cancer, where the disruption of C3a/C3aR axis caused a defect in the immune infiltration and leading to inhibition of tumor growth." (PMID 35173724, 2022). "Highly expressed C3 was found in tumor metastatic models and associated with tumor growth." (PMID 36071851, 2022). "Strikingly, mice deficient in C1q, C4, or C3 displayed decreased tumour growth." (PMID 34572075, 2021). "Mice deficient in C1q, C3, and C4 displayed decreased tumor growth." (PMID 33193442, 2020). "Finally, intracellular activation of complement C3 contributed to tumor growth via the modulation of tumor associated macrophages." (PMID 31931851, 2020). "The important role of C activation in the control of tumor growth was supported by the finding that radiotherapy failed to exert a protective effect against the tumor in mice deficient in either C3, or in C3a or C5a receptors, suggesting the critical contribution of locally released C3a and C5a." (PMID 30319647, 2018). "The C3 staining was scattered and mainly associated with tumour-infiltrating cells." (PMID 26831747, 2016). "Some markers, such as calcium, magnesium, and C3-complement, were associated with tumor numbers." (PMID 25853295, 2015). "Moreover, the ablation of C1q, C4, and C3 in mice was associated with decreased tumor growth." (PMID 38339243, 2024). "Mena loss also resulted in downregulation in the expression of genes that encode immunomodulatory secretory proteins that are part of the complement system, such as PTX3 and C3, suggesting that Mena may regulate immunosurveillance via the tumour-associated microenvironment." (PMID 36959177, 2023). "Furthermore, high expression levels of C3, C5, C3AR1, and C5AR1 are significantly (p < 0.05) associated with tumor subtypes in KIRC, LUAD, LUSC, and STAD, while tumor stages of BRCA are significantly (p < 0.05) associated with the expression of C3, C5, and C5AR1." (PMID 34439277, 2021). "In addition, the complement alternative pathway was also activated when complement C3 bound to the tumor cell receptor in vitro, resulting in the formation of the membrane attack complex (C5b-9) to destroy the tumor cell membrane lipid bilayer and cause the tumor cell to be lysed." (PMID 25017204, 2014). "The C3 components of the complement on the surface of the tumor cell are recognized by macrophages through complement receptors CR3 and CR4 (CRs), which results in increased FcγR-mediated phagocytic activity." (PMID 40821768, 2025). "Malassezia infection has been reported to activate mannose-binding lectin, triggering a complement cascade, particularly promoting the production of the oncogenic C3 complement, which facilitates tumor growth." (PMID 41304278, 2025). "Following doxorubicin-induced tumour cell death, C3 activation was also shown to modulate anti-tumour immune responses through inducing the recruitment of ICOSL expressing B-cells via the CR2 receptor expressed on B-cells." (PMID 39765018, 2025). "The opsonization of tumor cells with the complement component C3, along with the generation of pro-inflammatory mediators C3a and C5a, activates the cytotoxic activity of macrophages." (PMID 40821768, 2025). "Deletion of C3 or C5aR1 or administration of a C5aR1 inhibitor impaired tumour infiltration of adoptively transferred T cells, increasing tumour cell survival." (PMID 39765018, 2025). "Among its various components, complement component 3 (C3) has been studied relative to tumorigenesis and effects on the tumor microenvironment (TME)." (PMID 39964754, 2025). "It is important to note, however, that KPC cells injected into mice retain the C3 gene, and are thus capable of producing C3 locally within the tumor." (PMID 40198138, 2025). "Together with the proliferative-insensitive nature of C3 to enzalutamide, these findings implicate C3/myCAF in supporting tumor cell dissemination and the development of castration-resistant PCa." (PMID 41327318, 2025).